SLC30A8 (solute carrier family 30 member 8)
Description:
Proton-coupled zinc ion antiporter mediating the entry of zinc into the lumen of pancreatic beta cell secretory granules, thereby regulating insulin secretion.
Synonyms: ZnT-8; ZNT8
Tractability: Antibody: UniProt places it where antibodies can reach, with high confidence; its Gene Ontology location is reachable by antibodies, with high confidence; UniProt predicts a signal peptide or a membrane-spanning region; the Human Protein Atlas places it where antibodies can reach.
Gene: Protein-coding gene on chromosome 8 (116,950,273 to 117,176,714, forward strand). Ensembl gene ENSG00000164756.
Subcellular location: Cytoplasmic vesicle, secretory vesicle membrane; Cell membrane
Subcellular location (Human Protein Atlas): Plasma membrane; Vesicles
Pathways (Reactome):
Metabolism of proteins: Insulin processing
Transport of small molecules: Zinc efflux and compartmentalization by the SLC30 family
Gene Ontology:
Molecular function: protein binding; zinc ion transmembrane transporter activity; zinc:proton antiporter activity; zinc ion binding; monoatomic cation transmembrane transporter activity; protein homodimerization activity
Biological process: insulin secretion; response to glucose; zinc ion import into organelle; zinc ion transport; glucose homeostasis; insulin processing; intracellular zinc ion homeostasis; positive regulation of insulin secretion; regulation of vesicle-mediated transport; response to zinc ion; zinc ion import across plasma membrane; zinc ion transmembrane transport; monoatomic cation transport; response to interleukin-1; response to type II interferon; transmembrane transport
Cellular component: Golgi apparatus; plasma membrane; secretory granule; secretory granule membrane; transmembrane transporter complex; cytoplasmic vesicle; Golgi membrane; membrane; transport vesicle membrane; vesicle membrane
Genetic constraint (gnomAD): Loss-of-function variants: 23 observed, 35.37 expected, observed/expected ratio (o/e) 0.65, 90% interval 0.47 to 0.92. The upper end of that interval is the gene's LOEUF score, 0.92, which puts it in group 3 of 6, group 1 being the genes least tolerant of losing a copy. Missense variants: 402 observed, 435.54 expected, observed/expected ratio (o/e) 0.92, 90% interval 0.85 to 1. Synonymous variants: 151 observed, 169.44 expected, observed/expected ratio (o/e) 0.89, 90% interval 0.78 to 1.02.
Homologues: Orthologues: chimpanzee SLC30A8 (99% identical), macaque SLC30A8 (95% identical), rabbit SLC30A8 (88% identical), pig SLC30A8 (88% identical), dog SLC30A8 (86% identical), mouse Slc30a8 (80% identical), rat Slc30a8 (78% identical), tropical clawed frog slc30a8 (58% identical), zebrafish slc30a8 (53% identical), Drosophila melanogaster ZnT63C (23% identical). Paralogues in human: SLC30A2 (48% identical), SLC30A3 (42% identical), SLC30A4 (37% identical), SLC30A1 (23% identical), SLC30A10 (22% identical), SLC30A5 (19% identical), SLC30A6 (17% identical), SLC30A7 (17% identical).
Diseases named in the same sentence as SLC30A8 in open-access papers:
SLC30A8 is named in the same sentence as 42 diseases in open-access papers, as found by Europe PMC text mining. Sharing a sentence is not in itself a finding about the gene and the disease. The quoted sentences say what the papers report.
type 2 diabetes (96 papers, 2007 to 2025). "In summary, we confirm that SLC30A8 LoF is protective against type 2 diabetes, while partial LoF is associated with statistically significant improvements in glucose tolerance and insulin secretion." (PMID 41020949, 2025). "Genetic studies in participants of European descent identified two rare protein-truncating SLC30A8 variants, Arg138Ter and Lys34SerfsTer50, for which heterozygosity was associated with 53% and 80% risk reduction for type 2 diabetes, respectively." (PMID 41020949, 2025). "For example, one of the fine-mapped FTD risk loci, SLC30A8, encodes a zinc transporter and is a susceptible GWAS locus for type 2 diabetes." (PMID 41223260, 2025). "Genetic association studies have demonstrated that partial loss of SLC30A8 Function protects against type 2 diabetes in humans." (PMID 41020949, 2025). "The rs13266634 (T > C) polymorphism in the SLC30A8 gene has been extensively studied in type 2 diabetes mellitus (T2DM), with the C allele consistently associated with an increased risk of disease." (PMID 41009965, 2025). "We investigated the impact of complete loss of SLC30A8 Function on type 2 diabetes risk and related phenotypes in humans." (PMID 41020949, 2025). "Variations in zinc transporters are involved in multiple diseases, as indicated by the findings that a mutation in SLC30A8, which encodes ZnT8, affects type 2 diabetes risk, and that the knockout of ZIP13 influences beige adipocyte development." (PMID 41228448, 2025). "Common polymorphisms and rare heterozygous loss-of-function (LoF) mutations in SLC30A8 are associated with reduced risk of developing type 2 diabetes, a disease that is characterised primarily by impaired insulin secretion and sensitivity." (PMID 41020949, 2025). "Single nucleotide polymorphisms (SNPs) in the ZnT8 (SLC30A8) gene, particularly rs13266634, are associated with an increased risk of type 2 diabetes across various studied populations." (PMID 39195249, 2024). "Protection against type 2 diabetes isassociated with carrying a mutation in the zinc transportertype 8 gene (SLC30A8) that leads to the synthesis of a truncatedprotein." (PMID 36923482, 2023). "Genome-wide association studies of Type 2 Diabetes have also identified an association with a genetic variant in the SLC30A8 gene, which encodes a zinc transporter, ZnT8." (PMID 35451678, 2022). "Potapov V.A., Nosikov V.V., Shamkhalova M.N., Shestakova M.V., SmetaninaS.A., Bel’chikova L.N., Suplotova L.A. TCF7L2 rs12255372and SLC30A8 rs13266634 confer susceptibility to type 2 diabetes ina Russian population." (PMID 35434484, 2022). "In 2007, a genome-wide association study identified a non-synonymous polymorphism in the zinc transporter SLC30A8 gene as being linked with an increased risk of type 2 diabetes mellitus (T2DM)." (PMID 35017316, 2022). "A number of studies of patients with type 2 diabetes (T2D) from different populations have confirmed an association between a nonsynonymous polymorphism in SLC30A8, which encodes ZnT8, and elevated disease risk." (PMID 34027899, 2021). "SLC30A8 is also known as Zinc Transporter 8, it is a zinc efflux transporter, highly expressed only in the pancreas, its variants are associated with diabetes mellitus type 2." (PMID 33133517, 2020). "ZnT8 is encoded by SLC30A8 and the first genome-wide association study (GWAS) linking a polymorphism in this gene, on chromosome 8q24.11, with type 2 diabetes was published in 2007." (PMID 31444530, 2019). "The polymorphic variant rs13266634 (R325W) in the human ZnT8 gene SLC30A8 is strongly associated with Type 2 Diabetes risk." (PMID 31690008, 2019). "Scandinavian carriers of variants in SLC30A8 (Solute carrier family 30, member 8) are significantly less likely to develop type 2 diabetes even if obese —associations that have been replicated in people from other ancestries." (PMID 31002796, 2019).
type 2 diabetes (continued). "Although solute carrier family 30 (zinc transporter) member 8 (SLC30A8) gene 807C/T polymorphism is associated with an increased risk of type 2 diabetes mellitus (T2DM) risk, there remains some inconsistency between individual studies." (PMID 29875737, 2018). "The solute carrier family 30 member 8 gene (SLC30A8) is disease susceptibility gene of type 2 diabetes mellitus." (PMID 29791512, 2018). "The presence of ZnT8 autoantibodies has been shown to predict development of T1D, and genetic variations in the SLC30A8 locus have been linked to susceptibility to type 2 diabetes." (PMID 29064047, 2018). "This seemed an important question given that apparent differences in action have previously been described for other genome-wide association study–identified type 2 diabetes genes, such as SLC30A8 (37, –, 39), when modeled in mice." (PMID 29967064, 2018). "Five studies examined type 2 diabetes; zinc intake was found to interact independently with two polymorphisms in the zinc-transporter gene SLC30A8 to affect glucose metabolism indicators." (PMID 28218639, 2017). "This notion was challenged by a more recent study that focused on protein-truncating variants in SLC30A8 to determine the effect of loss-of-function on type 2 diabetes susceptibility." (PMID 28447115, 2017). "Single nucleotide polymorphisms (SNPs) in the human SLC30A8 gene have been associated, through genome-wide studies, with altered type 2 diabetes risk." (PMID 27390586, 2016). "Recent studies have demonstrated that DNA polymorphisms in the solute carrier family 30 member 8 (SLC30A8) gene confer the risk susceptibility to type 2 diabetes (T2D)." (PMID 25793017, 2015). "We confirmed associations of SNPs in KCNQ1, CDKN2A/CDKN2B, CENTD2 and SLC30A8 with type 2 diabetes in Han Chinese." (PMID 25587982, 2015). "This probably explains the linkage between the mutations of SLC30A8 zinc transporter (Zinc Transporter 8 [ZnT8]), which transports Zinc into the secretory granules, and type-2 diabetes." (PMID 26381880, 2015). "Although common SLC30A8 variants, believed to reduce ZnT8 activity, increase type 2 diabetes risk in humans, rare inactivating mutations are protective." (PMID 26178371, 2015). "ZnT8, which is expressed in pancreatic β cells, is essential for packaging insulin crystals, and variants in the SLC30A8/ZnT8 gene are associated with an increased risk for type 2 diabetes." (PMID 25007800, 2014). "Results from other investigations indicate that DUSP9 and SLC30A8 are common susceptibility loci for type 2 diabetes across various ethnicities." (PMID 24098730, 2013). "This gene is a zinc transporter related to SLC30A8, which has been implicated in type 2 diabetes, and zinc transport plays a role in insulin secretion by pancreatic -cells." (PMID 23825936, 2013). "The ZnT8 protein is encoded by the SLC30A8 gene, which is convincingly associated with type 2 diabetes risk at the single nucleotide polymorphism (SNP) rs13266634C>T, an amino acid substitution R325W." (PMID 22526605, 2012). "The association between SLC30A8 and susceptibility to type 2 diabetes appears at odds with the very mild phenotype of Slc30a8 KO mice." (PMID 22829903, 2012). "In humans the rs13266634 polymorphism in the SLC30A8 gene has been linked to not only type 2 diabetes but also impaired glucose tolerance, impaired proinsulin to insulin conversion and reduced first phase insulin secretion." (PMID 22829903, 2012). "We have recently shown that among type 2 diabetes-associated loci, risk alleles at MTNR1B, GCK and SLC30A8 confer a stronger rate of progression from normoglycemia to IFG than from IFG to type 2 diabetes." (PMID 22984506, 2012). "A non-synonymous polymorphism in the Slc30a8 gene encoding the insulin granule Zn2+ transporter Slc30a8 (ZnT8) has been associated with the risk of developing type 2 diabetes." (PMID 23056475, 2012).
type 2 diabetes (continued). "It is conceivable, however, that additional disturbances are required to unmask a more significant phenotype in Slc30a8 KO mice, such the presence of mutations in other type 2 diabetes-associated genes or zinc-deficient diets." (PMID 22829903, 2012). "Variants in TCF7L2 and SLC30A8 have previously been associated with type 2 diabetes in our Punjabi populations." (PMID 21949744, 2011). "SLC30A8 is a zinc efflux transporter expressed at high levels only in the pancreas; the GWAS revealed that variants of SLC30A8 are associated with type 2 diabetes." (PMID 21814517, 2011). "Overview of confirmed type 2 diabetes association results in the combined stage 1 and 2 samples for the widely replicated type 2 diabetes-associated variant SLC30A8 R325W (rs13266634)." (PMID 20525392, 2010). "SNPs from GIPR, TCF7L2, CRY2, GLIS3 and SLC30A8 were also associated with type 2 diabetes (p = 0.0487∼2.0×10−8)." (PMID 21103350, 2010). "In conclusion, we confirmed the association between PPARG, KCNJ11, CDKAL1, CDKN2A-CDKN2B, IDE-KIF11-HHEX, IGF2BP2, SLC30A8 variants and type 2 diabetes." (PMID 19862325, 2009). "We confirmed the effects of SNPs from PPARG, KCNJ11, CDKAL1, CDKN2A-CDKN2B, IDE-KIF11-HHEX, IGF2BP2 and SLC30A8 on risk for type 2 diabetes, with odds ratios ranging from 1.114 to 1.406 (P value range from 0.0335 to 1.37E-12)." (PMID 19862325, 2009). "A polymorphism in the SLC30A8 gene is associated with susceptibility to type 2 diabetes, although the molecular mechanism through which this phenotype is manifest is incompletely understood." (PMID 19479076, 2009). "Interest in the role of zinc in the pathogenesis of diabetes was re-ignited with the discovery, in five independent human genome-wide association studies, of an association between type 2 diabetes and a genetic polymorphism in the SLC30A8 gene." (PMID 19479076, 2009). "A coding non-synonymous polymorphism of SLC30A8 (R325W; rs13266634) has been demonstrated to be protective for type 2 diabetes and was shown to influence insulin secretion following an intravenous glucose challenge." (PMID 19096518, 2008). "Altogether, these analyses support that SLC30A8 LoF reduces type 2 diabetes risk through a mechanism of enhanced insulin secretion and improved overall beta cell function, and that the magnitude of this effect may be proportional to the degree of SLC30A8 LoF." (PMID 41020949, 2025). "Loss of SLC30A8 Function was associated with gene dosage-dependent protection from type 2 diabetes." (PMID 41020949, 2025). "Heterozygous loss of SLC30A8 Function confers protection from type 2 diabetes." (PMID 41020949, 2025). "Other noteworthy genes in our candidate list were APPL2, an adiponectin receptor associated with overweight and obesity in a Chinese population, DOCK5, a susceptibility gene for severe obesity, and SLC30A8, a zinc efflux transporter implicated in type 2 diabetes and obesity in Asians." (PMID 38355434, 2024). "Overall, disruption of zinc homeostasis has been associated with oxidative stress, inflammatory processes, dyslipidemia, and diabetes mellitus type 2, mostly through mechanisms mediated by the rs13266634 polymorphism in the SLC30A8 gene encoding zinc transporter ZnT8." (PMID 36986146, 2023). "Variants at the SLC30A8 locus are associated with type 2 diabetes (T2D) risk." (PMID 37502937, 2023). "Common variants in the SLC30A8 gene, encoding the secretory granule zinc transporter ZnT8 (expressed largely in pancreatic islet alpha and beta cells), are associated with altered risk of type 2 diabetes." (PMID 37396167, 2023). "SLC30A8 has also been implicated in type 1 and type 2 diabetes." (PMID 34775485, 2022). "Interestingly, SNPs in SLC30A8 are extremely associated with Type 2 diabetes and gender-specific schizophrenia." (PMID 36052323, 2022).
type 2 diabetes (continued). "Genetic association studies, including ours have demonstrated that the common single nucleotide polymorphisms in the SLC30A8 gene confer the risk susceptibility to type 2 diabetes (T2DM), while the rare loss-of-function variants in the gene have protective effects in the disease." (PMID 32681069, 2020). "Loss-of-function mutations in SLC30A8 seems to be strongly protective against type 2 diabetes." (PMID 30079052, 2018). "The second set of genes LIM homeobox transcription factor 1 alpha (LMX1A), solute carrier family 30 member 8 (SLC30A8) is associated with insulin metabolism and resistance, a feature of some patients in whom type 2 diabetes is an accompanying comorbidity of vestibular neuritis." (PMID 30079052, 2018). "Evidence for the association of SLC30A8 variants with type 2 diabetes (T2D) is inconclusive." (PMID 27896278, 2016). "In addition, the current study also replicated the significant associations of two other genes (CDKN2A/CDKN2B and SLC30A8) with type 2 diabetes susceptibility, which was consistent with the observations from other studies in Han Chinese." (PMID 25587982, 2015). "In addition, genome-wide association (GWA) studies in humans have linked a non-synonymous single nucleotide polymorphism (SNP) within the SLC30A8 gene with increased susceptibility for the development of type 2 diabetes and gestational diabetes." (PMID 22829903, 2012). "Of these loci, only GCK, MTNR1B, DGKB, GCKR, ADCY5 and PROX1 (besides TCF7L2 and SLC30A8) were associated with type 2 diabetes at genome-wide significance levels, with several others (but not all) showing a consistent trend but not meeting the same stringent statistical threshold." (PMID 22984506, 2012). "A polymorphic variant in SLC30A8 is associated with altered susceptibility to type 2 diabetes." (PMID 22829903, 2012). "In addition, SNPs from PPARG, KCNJ11, CDKAL1, IDE-KIF11-HHEX, IGF2BP2 and SLC30A8 were also moderately associated with type 2 diabetes, with ORs ranging from 1.114 to 1.282 (P<0.05)." (PMID 19862325, 2009). "Genetic variants of SLC30A8 are associated with an increased risk of type 2 diabetes mellitus (T2DM)." (PMID 41425581, 2025). "Effect variant in SLC30A8 gene may potentially protect against type 2 diabetes." (PMID 38626572, 2024). "Common variants in SLC30A8 have been identified through genome-wide association studies (GWAS) in humans and affect type 2 diabetes (T2D) risk." (PMID 37396167, 2023). "The solute carrier family 30 member 8 gene (SLC30A8) encodes a zinc transporter in the pancreatic beta cells and the major C-allele of a missense variant (rs13266634; C/T; R325W) in SLC30A8 is associated with an increased risk of type 2 diabetes (T2D)." (PMID 29093761, 2017). "Importantly, the current results may provide an explanation for the recent finding that rare loss-of-function mutations in the SLC30A8 gene in man are associated with protection against type 2 diabetes." (PMID 24865615, 2014). "Using a recall-by-genotype study design, we conducted phenotyping studies in the PGR for several metabolic parameters to understand the physiological mechanisms by which SLC30A8 LoF protects against type 2 diabetes." (PMID 41020949, 2025). "While SLC30A8 has been primarily studied in the context of glucose homeostasis and type 2 diabetes, our data extend its possible role to lipid dysregulation, highlighting a broader contribution to the metabolic disturbances that characterise android obesity." (PMID 41009965, 2025). "We identify many genes with a well-defined role in relation to type 2 diabetes (e.g. ABCC8, SLC30A8), including 48 of the 132 type 2 diabetes effector genes from the Type 2 Diabetes Knowledge Portal." (PMID 38967666, 2024). "The SLC30A8 gene on chromosome 8q24.11 has garnered significant attention in the study of type 2 diabetes (T2D)." (PMID 38694942, 2024).